RBP4 (retinol binding protein 4)
Diseases named in the same sentence as RBP4 in open-access papers (continued):
Sharing a sentence is not in itself a finding about the gene and the disease.
Insulin resistance (continued). "In addition to its proinflammatory function, RBP4 mainly causes insulin resistance and is linked to various chronic diseases." (PMID 29495330, 2018). "However, while associations between plasma RBP4 levels, TG levels and insulin resistance have been shown in many human studies, while other studies report an insulin resistance-independent association between plasma RBP4 and TG levels." (PMID 29747616, 2018). "RBP4 was found to interrupt the insulin signaling cascade causing insulin resistance." (PMID 29747616, 2018). "RBP-4 is associated with both insulin resistance and increased adiposity." (PMID 28670222, 2017). "Accordingly, the insulin resistance biomarkers such as serum insulin, leptin, adiponectin, retinol binding protein 4 (RBP4) and lipid profile were assayed, and the underlying transcriptomic changes induced by C.nutans on hepatic insulin resistance-related genes were evaluated." (PMID 26924713, 2016). "RBP4 as a novel adipokine, it has also been associated with obesity-related co-morbidities including insulin resistance, dyslipidemia, type 2 diabetes and coronary heart disease, while these obesity-related diseases are well-established risk factor for breast cancer." (PMID 28002423, 2016). "Additionally, the ApoE, PTP1B and RBP4 lipometabolic regulators linked with obesity and insulin resistance were upregulated in PLB4 mouse liver, suggesting decreased hepatic insulin sensitivity." (PMID 27138913, 2016). "Finally, a child intervention study demonstrated that the loss of fat mass resulted in reduced RBP4 level that was accompanied by decreases in levels of systemic inflammation and insulin resistance." (PMID 25479076, 2014). "Recent studies demonstrated that RBP4 levels were increased in obese and insulin-resistant humans and mouse models; additionally, a genetic or pharmacologic elevation of serum RBP4 causes insulin resistance in normal mice." (PMID 24559154, 2014). "Several RBP4 gene variants are associated with adiposity and insulin resistance." (PMID 24733068, 2014). "Our data suggest that previously reported associations between RBP4 and insulin resistance may be influenced by triglyceride and FFA serum concentrations." (PMID 24968098, 2014). "Reduction of RBP4 could be a protective mechanism to prevent the organism from developing insulin resistance in an acute inflammatory state and weight loss." (PMID 24099047, 2013). "RBP4 has been implicated in these alterations, especially insulin resistance." (PMID 23460908, 2013). "So, in rodents, RBP4 is closely linked to insulin resistance." (PMID 23781325, 2013). "Liver RBP-4 and visfatin/Nampt might also be associated with insulin resistance, but more studies are required to further investigate and confirm the association." (PMID 24367155, 2013). "The following aspects were explored: 1) the potential association of serum RBP4 levels with insulin resistance; 2) metabolic parameters as independent predictors of RBP4; and 3) the involvement of RBP4 in contributing to the atherogenicity of both LDL and HDL particles." (PMID 24223837, 2013). "Retinol binding protein 4 (RBP4), secreted primarily by the liver and adipocytes, is a recently identified adipokine apparently linked to obesity and its comorbilities in humans, especially insulin resistance, T2D, and certain components of MetS." (PMID 24223837, 2013). "Some evidence provides linking resistin and RBP4 with insulin resistance or cardiovascular risk." (PMID 23970879, 2013). "RBP4 has been previously related to insulin resistance and clinical markers of increased cardiovascular risk such as intima-media thickness (IMT), not only in high-risk individuals including hypertensive and type 2 diabetic and hypertensive patients, but also in the general population." (PMID 22938533, 2012). "RBP-4 is associated with altered insulin resistance in critical illness." (PMID 22272381, 2012).
Insulin resistance (continued). "Experiments in mice indicated that elevated RBP4 levels cause insulin resistance, suggesting that the improvement of glucose metabolism by PPARγ activation may be through the reduction of circulating RBP4 levels." (PMID 23145084, 2012). "Finally, the A allele of RBP4 −803GA polymorphism was associated with a higher rate of insulin resistance in HIV-infected patients receiving anti-retroviral therapy." (PMID 23145084, 2012). "RBP4 was reported to be elevated in patients with pregnancy-induced hypertension, possibly as a result of perturbed maternal glucose metabolism, and in women with hypertension caused by insulin resistance." (PMID 22416803, 2012). "In addition, an elevated serum concentration of RBP4 has been linked to insulin resistance as well as subclinical inflammation." (PMID 22151790, 2011). "The strong associations with hepatic and renal function, insulin resistance and acute mortality collectively suggest a role of RBP4 in the pathogenesis of critical illness, possibly as a negative acute phase reactant, and allow a proposition as a potential novel biomarker for ICU patients." (PMID 20932285, 2010). "Elevated levels of RBP4 were shown to cause insulin resistance in muscles and liver." (PMID 20625434, 2010). "Decreasing levels of RBP4 were associated previously with altered insulin resistance." (PMID 19589139, 2009). "Adiponectin and RBP4 are associated with altered insulin resistance in critical illness." (PMID 19589139, 2009). "However, some contrasting results were reported regarding the association between circulating RBP4 and insulin resistance." (PMID 19589139, 2009). "In support of this possibility, identification of regulatory single nucleotide polymorphisms in the RBP4 gene associated with type 2 diabetes has been recently reported, while correlations of RBP4 with insulin resistance have been confirmed in experimental clinical approaches in humans." (PMID 19460132, 2009). "Interestingly, liver protein abundance of retinol-binding protein 4 (RBP4), described to be associated with insulin resistance and adipose tissue inflammation, was lowered with apoA-IV administration (−1.9-fold), thus pointing to apoA-IV being a novel regulator of RBP4." (PMID 40032158, 2025). "However, increasing numbers of studies have indicated that circulating RBP4 levels are associated with cardiometabolic diseases such as obesity, insulin resistance, hyperlipidaemia, hypertension, chronic liver diseases, atherosclerosis and cardiovascular disease." (PMID 38520616, 2024). "Furthermore, RBP4 may cause insulin resistance by activating both innate and adaptive immune responses." (PMID 38520616, 2024). "Besides the adipokines and cytokines roles in the induction of insulin resistance, it has been found that elevated level of RBP4 may linked to obesity, and other risk factor, such as cardiovascular disease, hypertension, and hyperlipidemia." (PMID 36776154, 2023). "However, several studies could not reproduce these findings, generating some controversy on whether RBP4 is indeed causative for developing insulin resistance." (PMID 36030930, 2022). "In addition, RBP4 was found to cause cardiomyocyte hypertrophy, which may mediate a vicious cycle between insulin resistance and heart failure." (PMID 35309061, 2022). "Hence, RBP4’s causal role in inducing insulin resistance is still vividly debated within the field." (PMID 33790810, 2021). "In addition, there are different polymorphisms of RBP4, which may influence the association between RBP4 and insulin resistance." (PMID 31051472, 2019). "The overexpression of RBP4 in wild-type mice causes insulin resistance while genetic depletion of Rbp4 improves insulin sensitivity, suggesting that the depleting level of RBP4 could be helpful in the treatment of T2DM, and levels of RBP4 could serve as a biomarker for T2DM." (PMID 29740397, 2018).
Insulin resistance (continued). "Several clinical studies have shown that increased circulating levels of RBP4, which mainly functions as a specific transport protein of retinol (vitamin A) in the circulation, are associated with either hyperandrogenism or insulin resistance in women with PCOS." (PMID 29719598, 2018). "Besides the bone metabolism role, vitamin D also has the ability to reduce the level of RBP4 and to provide vascular protection, which is partly associated with inhibiting cholesterol biosynthesis, relieving inflammation reaction, improving insulin resistance, and increasing insulin sensitivity." (PMID 30186876, 2018). "This may relate to the strong associations of RBP-4, BMI and insulin resistance." (PMID 26110385, 2015). "Studies in mice suggest that elevated serum RBP4 could play a causal role in insulin resistance." (PMID 25890223, 2015). "In addition to its effects on insulin resistance, positive associations have also been documented between RBP4 and established cerebrovascular disease (CVD) risk factors including, metabolic syndrome, overall/central obesity, dyslipidemia, and inflammatory markers." (PMID 25479076, 2014). "Hence, it has yet to be established whether RBP4 may serve as a risk marker for insulin resistance and type 2 diabetes and to what extent it is associated with MetS." (PMID 24559154, 2014). "Since evidence showing relationship of RBP4 with cardiometabolic risk in human is inconsistent, there is still argument on whether elevated RBP4 levels contribute to the pathogenesis of abnormal glucose homeostasis or insulin resistance." (PMID 23970879, 2013). "However, the relationship between PPARγ or RBP4 polymorphism and insulin resistance or dyslipidemia in HIV-infected patients receiving HAART remains unclear." (PMID 23145084, 2012). "Additionally, high levels of RBP4 have been linked to the development of insulin resistance." (PMID 22151790, 2011). "Mediation analysis was conducted to assess the mediating role of RBP4 in the relationship between UA and homeostasis model assessment of insulin resistance (HOMA-IR)." (PMID 42257404, 2026). "RBP4 contributes to the advancement of insulin resistance via immune and inflammatory processes in adipose and vascular tissues." (PMID 41227378, 2025). "In obesity and T2DM, RBP4 is elevated in adipose tissue, contributing to systemic insulin resistance and inflammation through Toll-like receptor-4 (TLR4)." (PMID 40951890, 2025). "Overexpression or injection of RBP4 caused glucose intolerance and insulin resistance, suggesting RBP4 acts as an adipokine connecting obesity with insulin resistance." (PMID 40951890, 2025). "These reductions in RBP4 levels were significantly correlated with improvements in insulin resistance markers, as evidenced by decreased HOMA-IR values (P = 0.001)." (PMID 40276651, 2025). "RBP4 also activates antigen-presenting cells, leading to adipose tissue inflammation and systemic insulin resistance, and the muscle-adipose tissue crosstalk mediated by RBP4 exacerbates metabolic dysfunction." (PMID 40276651, 2025). "RBP-4 also increases insulin resistance by reducing phosphatidylinositol 3-phosphate kinase, leading to the formation of pancreatic adenocarcinoma." (PMID 41007818, 2025). "RBP4 is increased with insulin resistance; it increases adipocyte basal lipolysis and reduces the ability of insulin to suppress lipolysis (which also leads to ectopic liver fat accumulation) and has been implicated in immune stimulation." (PMID 41416660, 2025). "Beyond its classical role in retinol transport, RBP4 influences insulin resistance, inflammation, lipid metabolism, mitochondrial function, and cellular apoptosis in both skeletal and cardiac muscles." (PMID 40276651, 2025).
Insulin resistance (continued). "RBP4 contributes to the development of insulin resistance by impairing insulin signalling in skeletal muscle and adipose tissue, upregulating lipolysis and inflammation in adipose tissue and increasing gluconeogenesis and lipid accumulation in the liver." (PMID 39318364, 2024). "A positive relationship between BMD and RBP-4 is indicated, while an inverse relationship is indicated between markers of insulin resistance, bone turnover, and current BMD." (PMID 39124655, 2024). "RBP-4, a known marker for insulin resistance, was increased in the CON-I and SIT-N groups compared to CON-N." (PMID 39074126, 2024). "Previous studies have shown that high RBP4 gene expression can induce insulin resistance and promote the development of T2DM." (PMID 38520616, 2024). "In contrast, RBP4 promotes insulin resistance in skeletal muscle, adipocytes, and hepatocytes in addition to indirectly promoting insulin resistance by stimulating cytokines secretion by macrophages." (PMID 38673873, 2024). "In this review, we update and summarize recent studies examining the relationship between RBP4 and T2DM and the role of RBP4 in insulin resistance and pancreatic β-cell function." (PMID 38520616, 2024). "By overexpressing RBP4 in wild-type rats or injecting recombinant human RBP4, insulin resistance can be induced in rats, whereas RBP4 gene deletion can enhance insulin sensitivity." (PMID 39698033, 2024). "Studies have reported that the expression of RBP4 in liver and adipose tissue has different effects on insulin resistance." (PMID 38520616, 2024). "Since RBP4 was first reported to be closely related to insulin resistance, an increasing number of studies have focused on the association between circulating RBP4 levels and insulin resistance." (PMID 38520616, 2024). "The effects of RBP4 on whole-body glucose metabolism were further proven by studies using muscle-specific RBP4 transgenic mice with glucose intolerance and insulin resistance." (PMID 38672227, 2024). "In comparison to adropin and irisin, RBP4 is involved in the pathogenesis of insulin resistance by exerting numerous deleterious metabolic actions in adipose tissue, skeletal muscle, and the liver." (PMID 39318364, 2024). "Adipose tissue is another important organ for the mechanistic link between RBP4 and insulin resistance." (PMID 38520616, 2024). "In contrast to the positive associations reported for the human studies considered above, some studies have reported an insignificant correlation between circulating RBP4 levels and insulin resistance." (PMID 38520616, 2024). "Retinol binding protein 4 (RBP 4) is an adipokine produced in the liver and has been implicated in obesity-induced insulin resistance and inflammation." (PMID 38541892, 2024). "Potential contributors to the observed outcomes include elevated RBP4, TG, insulin resistance, and BMI." (PMID 38732128, 2024). "Higher circulating levels of RBP4 have been reported in visceral obesity, insulin resistance, prediabetes, T2DM, non-alcoholic fatty liver disease (NAFLD), and the metabolic syndrome." (PMID 39318364, 2024). "Regarding the transportation of vitamin A, it enters the circulation when retinol binds to retinol-binding protein 4, which plays an important role in insulin resistance, dyslipidaemia, obesity and diabetes." (PMID 39469581, 2024). "In summary, LCN2 and RBP4 exert similar effects in insulin resistance and glucose metabolism, while LCN13 and MUP1 on the other hand exert opposite effects." (PMID 38673873, 2024). "Supporting the key role of RBP4 in metabolic diseases, its therapeutic targeting has successfully controlled the development of hypertension and insulin resistance in animal models." (PMID 38275649, 2024). "The transfer of RBP4-activated APCs into normal mice is sufficient to induce adipose tissue inflammation, insulin resistance, and glucose intolerance." (PMID 39698033, 2024).
Insulin resistance (continued). "Research conducted on animals indicates that insulin resistance can be induced by transgenic over-expression of human RBP4 or injection of recombinant RBP4 into wild-type mice; conversely, deletion of the RBP4 gene results in increased insulin sensitivity." (PMID 38732128, 2024). "Retinol binding protein 4 is negatively correlated with the expression of GLUT4 during insulin resistance and BBR can significantly reduce the serum retinol binding protein 4 levels and upregulate the expression of GLUT4 in T2DM rats." (PMID 38957396, 2024). "A Thai study showed that high circulating RBP4 was a predictor of insulin resistance and the severity of coronary artery disease (CAD) in T2DM with CAD." (PMID 36835525, 2023). "Another described mechanism in NAFLD/NASH pathogenesis is insulin resistance through hepatokines such as fetuin A, fetuin B, retinol-binding protein 4 (RBP4), and selenoprotein P." (PMID 37374340, 2023). "RBP4, an adipokine related to obesity and insulin resistance, has been proposed as a potential biomarker of inflammatory activity in obesity and chronic periodontitis." (PMID 37798684, 2023). "For example, retinol-binding protein 4 (RBP4) contributes to insulin resistance and heart failure by activating the TLR4/MyD88 signaling pathway." (PMID 37113698, 2023). "Studies have shown that RBP4 can lead to insulin resistance and affect protein anabolism in skeletal muscle indirectly, particularly under the stimulation of peroxisome proliferator-activated receptor-gamma (PPARγ) agonists." (PMID 37525169, 2023). "In diabetes, an association of RBP4 concentration has been documented with the magnitude of insulin resistance, suggesting increased levels of RBP4 predicts insulin resistance." (PMID 36271990, 2023). "We have also examined the potential association between changes in insulin resistance and fasting and postprandial PYY and GLP1 hormones, adiponectin, RBP4, FGF21 and CRP over 3 years of follow-up." (PMID 37055514, 2023). "Previousstudies have confirmed that RBP4 can be involved in the development of T2DM byinducing insulin resistance and impairing islet β-cell function." (PMID 39077416, 2023). "In animal models, RBP4 appears to be pro-inflammatory in adipose tissue, inducing cytokine secretion and systemic insulin resistance." (PMID 36983885, 2023). "In 2005, an important study sparked new interest in the relationship between RBP4 and insulin resistance, the pathophysiological driver to type 2 diabetes." (PMID 35334893, 2022). "Perhaps the severity of preeclampsia can be attributed to the insulin resistance that is mediated by high levels of RBP4." (PMID 36558360, 2022). "In particular, the adipokines resistin, leptin, PAI-1 and retinol binding protein 4 (RBP4) induce insulin resistance in megakaryocytes by interfering with IRS-1 expression with a negative impact on insulin signalling in platelets." (PMID 35250588, 2022). "In adipose and vascular tissues, RBP4 is involved in the progression of insulin resistance by regulating the immunity and inflammatory reaction." (PMID 35369314, 2022). "Retinol-binding protein 4 (RBP4), a reliable marker of insulin resistance, was identified, and is possibly associated with the onset mechanism of acute graft-versus-host disease (aGvHD) and/or skin GvHD." (PMID 35977993, 2022). "Initially, RBP4 was found to be involved in the pathogenesis of insulin resistance in type 2 diabetic patients." (PMID 35309061, 2022). "Serum and AT RBP4 levels were also suggested to contribute to systemic insulin resistance by enhancing adipocyte basal lipolysis and activating AT proinflammatory macrophages." (PMID 35406450, 2022). "Nevertheless, the contribution of AT-derived RBP4 to the increased levels of circulating RBP4 in states of insulin resistance was contested." (PMID 35406450, 2022). "Asian propolis compounds are good inhibitors of RBP4 levels, possibly decreasing insulin resistance in T2DM patients." (PMID 35807241, 2022).